IL6 (interleukin 6)
Diseases named in the same sentence as IL6 in open-access papers (continued):
Sharing a sentence is not in itself a finding about the gene and the disease.
COVID-19 (continued). "Further, the only assay authorized for clinical use in risk-stratifying COVID-19 (IL-6 measured in blood), substantially underperformed our proposed 6-mRNA model here." (PMID 35042868, 2022). "Severity group-specific associations between miRNAs and COVID-19-associated CC (e.g., IL6, CCL20) or clinical hallmarks of COVID-19 (e.g., neutrophilia, hypoalbuminemia) separated patients with similar CC levels but different disease severity." (PMID 34957382, 2022). "The activation of IL-1β and IL-6 in COVID-19 has been associated with “cytokine storms”, which can have severe biological and clinical consequences." (PMID 35162148, 2022). "We also measured secreted IL-6, associated with the acute inflammatory response in COVID-19 and influenza, as well as the increased production of anti-inflammatory IL-10, which maintains immune homeostasis." (PMID 35962146, 2022). "Recent research has shown that the common Asian haplotype C-T-T, represented by alleles rs1800796, rs1524107, and rs2066992, reduces the risk of severe COVID-19 via reduced IL6 expression." (PMID 35165525, 2022). "An array of studies have shown early increased concentrations of inflammatory cytokines, including of IL-1β, IL-4, and IL-6, are associated with more severe COVID-19." (PMID 38566903, 2022). "The meta-analysis showed that each increase in the IL-6 level of 1 pg/mL significantly increased the risk of mortality of COVID-19 patients (crude HR = 1.0027; 95% CI 1.0013–1.0041; p = 0.0002)." (PMID 35215138, 2022). "The aim of this study was to assess the mortality risk in hospitalized COVID-19 patients according to IL-6 serum levels and new-onset atrial fibrillation (AF) according to PaO2/FiO2 stratification." (PMID 35454369, 2022). "Complicated cases of COVID-19 exhibit higher levels of proinflammatory cytokines, such as IL6 and IFNG, making them more susceptible to neurological complications." (PMID 35794518, 2022). "A cytokine storm characterized by elevation in the serum concentrations of several pro-inflammatory cytokines is a hallmark of COVID-19, with IL-6 and IL-10 being significantly elevated in those with critical disease." (PMID 35335635, 2022). "The increased mortality of many severely ill COVID-19 patients has been linked to the excess production of proinflammatory cytokines (e.g., IL-6, IL-1β, TNF-α, and interferon) upon SARS-CoV-2 infection, causing multiple organ failure." (PMID 36173315, 2022). "Increased production of proinflammatory cytokines, including IL-6, is linked to autoimmune disorders and other key factors in the cytokine storm in patients with severe COVID-19." (PMID 35887067, 2022). "We found that the genetic variant rs2069837 in IL-6 was protective against critical COVID-19 (combined p = 4.64 × 10−16, OR = 0.49)." (PMID 35368020, 2022). "Other studies of blood demonstrated that severe COVID-19 is associated with an increase in IL-6, activated macrophages and neutrophils and a T cell lymphopenia that contribute to lower proportions of antigen-specific CD4+ and CD8+ T cells." (PMID 36211412, 2022). "Among the long list of cytokines/chemokines, IL-6 has been recognized as a key COVID-19-associated cytokine." (PMID 35248063, 2022). "Several studies showed that patients with NAFLD have intrinsically higher C-reactive protein (CRP) and IL-6 serum concentrations, which are both associated with COVID-19 severity." (PMID 35743825, 2022). "In severe COVID-19 patients, the diagnostic performance was good for IL-6 (AUC = 0.844), fair (acceptable) for IL-18 (AUC = 0.785) and IL-35 (AUC = 0.742), and poor for IL-1β (AUC = 0.604)." (PMID 36675695, 2022). "Various inflammatory markers were associated with COVID-19 progression, but the hallmark of hyperinflammatory response is interleukin-6 (IL-6) acting as a central player in immune regulation, inflammation, and infection." (PMID 35873360, 2022).
COVID-19 (continued). "The cytokine storm caused by COVID-19 increases the level of IL-6, which can lead to high levels of iron and macrophage activation." (PMID 36293381, 2022). "Targeting inflammation such as IL-6 is a promising tool for the treatment of COVID-19 and provides evidence of the biological mechanism underlying the clearance of COVID-19." (PMID 36403042, 2022). "Sixteen studies analyzed the association between the IL-6 level and severe COVID-19; these reported OR values from a logistic regression analysis." (PMID 35215138, 2022). "In fact, in a prospective meta-analysis of clinical trials of patients hospitalized for COVID-19, it was concluded that administration of IL-6 antagonists was associated with lower all-cause mortality with a cutoff of 28 days." (PMID 35746958, 2022). "To date, elevated serum levels of CXCL-10 and IL-6 have been consistently reported in patients with COVID-19, as these are associated with an increased disease severity and risk of mortality." (PMID 35237279, 2022). "In conclusion, both asymptomatic SARS-CoV-2 infected blood donors and patients with severe COVID-19 share an inflammatory profile; however, high levels of IL-6, IL-10, and CCL5 were significantly associated with severe infection outcomes." (PMID 36287506, 2022). "It is worth noting that IL-6 is one of the most important inflammatory mediators in COVID-19, with its levels being linked to the viral load." (PMID 35054471, 2022). "This meta-analysis analyzed the association between the levels of TNF-α, IL-6, and vitamin D and the severity and mortality of COVID-19." (PMID 35215138, 2022). "In this study, we propose an IL-6 test strip combined with a spectrum-based optical reader for early recognition of COVID-19-infected patients at imminent risk of acute respiratory failure requiring mechanical ventilator support." (PMID 35242747, 2022). "There are many studies underlining the importance of NLR, ANC, and IL-6 levels in determining disease severity and estimating prognosis in COVID-19." (PMID 36261210, 2022). "The most important of all factors associated with the cytokine storm is IL-6 (interleukin-6), the level of which correlates strongly with the risk of death from COVID-19." (PMID 35054856, 2022). "It has well established that severe COVID-19 patients are generally associated with an increased cytokine-release syndrome, which further elevated interleukin-6 (IL-6)." (PMID 35250581, 2022). "It seems that the cause of mortality in the COVID-19 patients is respiratory failure due to the elevation of cytokine release especially IL-6." (PMID 35656183, 2022). "It is worth mentioning that out of all the cytokines mentioned, IL-6 and IL-2 are strongly associated with the severity of the disease, meaning that they are more elevated in critically ill COVID-19 patients than in ordinary COVID-19 patients." (PMID 36295093, 2022). "A characteristic problem occurring in coronavirus disease 2019 (COVID-19) are excessive elevations of pro-inflammatory cytokines such as interleukin-6 (IL-6) and C-reactive protein (CRP) which are associated with worse clinical courses." (PMID 36263035, 2022). "As a mediator of an inflammatory response, one study finds higher IL-6 levels in patients with complicated COVID-19 associated with higher mortality risk." (PMID 35855892, 2022). "Serum IL-6 was elevated in adult patients with COVID-19 and its level was associated with severity and prognosis." (PMID 36298826, 2022). "Severe COVID-19 is particularly associated with pronounced elevations of IL-6, and IL-6 blockade has proven efficacy in severe disease." (PMID 35308241, 2022). "The results of the meta-analysis were that each increase in the IL-6 level of 1 pg/mL significantly increased the risk of developing severe COVID-19 (aOR = 1.0284; 95% CI 1.0130–1.0441; p = 0.0003)." (PMID 35215138, 2022).
COVID-19 (continued). "The results showed that each increase in the IL-6 level of 1 pg/mL significantly increased the risk of developing severe COVID-19 (crude OR = 1.0643; 95% CI 1.0318–1.0979; p < 0.0001)." (PMID 35215138, 2022). "This being said, CRS is common in patients with COVID-19, and most importantly, high serum IL-6 constitutes a hallmark of respiratory failure, ARDS, and the worst clinical outcomes." (PMID 35250575, 2022). "A key proinflammatory mediator is the cytokine IL-6, which is linked to the severity and prognosis of COVID-19 (21, –, 23)." (PMID 35582921, 2022). "Recent studies of genetic factors have implicated several IL6 gene variations in pathogenesis of coronavirus infection 2019 (COVID-19), a disease where severity has a strong association with the likelihood of a cytokine storm." (PMID 35059462, 2022). "We found that fatal COVID-19 was associated with higher levels of IL6, IL10, IL22, CXCL10, CCL2, and CCL20 and lower levels of miR-495-3p, miR-451a, and miR-29b-3p." (PMID 34957382, 2022). "A characteristic problem occurring in COVID-19 is excessive elevations of pro-inflammatory cytokines (e.g. IL-6 and CRP) which are associated with worse clinical outcomes." (PMID 36263035, 2022). "Because the COVID-19–associated cytokine storm involves several cytokines in addition to IL-6, blocking multiple inflammatory mediators via JAK/STAT inhibition is a rational therapeutic approach." (PMID 36226977, 2022). "Although several mechanisms have been proposed, estrogen is shown to suppress pro-inflammatory cytokines such as IL-6, which is implicated in pulmonary vessel leakage and lung damage seen with COVID-19." (PMID 36548002, 2022). "When not inhibited by TIMP-3, due to low SIRT1 activity-mediated TIMP-3 reduction, ADAM17 causes the release of TNF-α and IL6 and contributes to inflammation and possibly to the development of an uncontrolled hyperinflammatory response in COVID-19." (PMID 35457123, 2022). "Of note, in this study, IL-6 level in saliva of COVID-19 was positively associated with ferritin and had a positive trend with other markers of COVID19 severity, D-Dimer and CRP, although not to a significant level (P = 0.1)." (PMID 36163397, 2022). "COVID-19 is associated with massive immune activation, with elevated levels of proinflammatory cytokine IL-6." (PMID 35812392, 2022). "In elderly individuals, AKI, IL-6 levels, and myocardial injury were equally associated with mortality, indicating the burden of COVID-19 with aging." (PMID 35957939, 2022). "A recent GWAS found that the genetic variant rs2069837 in IL-6 decreased the expression of IL-6 in the serum and was protective against critical COVID-19." (PMID 36204639, 2022). "Another report also suggested that the magnitude of cytokine secretion is associated with severity of COVID-19 and that postmortem lung samples showed higher endothelial expression of IL-6 and TNF-α in the diseased condition than in control condition." (PMID 34463916, 2022). "Elevated levels of interleukin-6 (IL-6) detected in the serum of the patients with severe acute respiratory stress associated with COVID-19." (PMID 35008377, 2022). "A review of risk factors for long COVID-19 stated that several biomarkers were elevated including D-dimer, interleukin-6 (IL-6), C-reactive protein, procalcitonin, and neutrophils count." (PMID 35458189, 2022). "Although it is the main cause of cytokine storms in COVID-19 patients, IL-6 has both anti-inflammatory and pro-inflammatory properties that play a complex role in COVID-19 pathology." (PMID 35843719, 2022). "Relating our results with the COVID-19 lung destruction, that appears to be associated with a cytokine storm with an increased IL-6 level." (PMID 35379329, 2022). "We further confirmed that higher levels of IL-6 in PDM patients with COVID-19 was associated with ICU admission and MV." (PMID 35898449, 2022).
COVID-19 (continued). "Lastly, high levels of interleukin 6 (IL-6) and interleukin 17 (Il-17) have been associated with concurrent COVID-19 and periodontal disease." (PMID 35224542, 2022). "Since severe COVID-19 is associated with high levels of IL-6, sepsis has been used as a prototype of critical illness for the understanding of severe COVID-19 pathogenesis." (PMID 35911748, 2022). "In our study, among the cytokines evaluated, only high levels of IL-6 were associated with the severity of COVID-19, confirming the relevance of this cytokine in the outcome of the disease." (PMID 35846757, 2022). "SSRIs decreased plasma levels of four of 16 tested inflammatory mediators, including interleukin (IL)-10, tumor necrosis factor (TNF)-α, and CCL-2, which are associated with COVID-19 severity, and IL-6, which highly plays a role in disease mortality." (PMID 36532776, 2022). "IL-6 also appears to be an important driver of monocyte HLA-DR loss, placing this cytokine at the centre of the immunopathological signature of COVID-19." (PMID 35386227, 2022). "Overall, high levels of TNF-α, IL-6, IL-8, and IL-10 have been associated with disease severity and poor survival from COVID-19." (PMID 34987205, 2022). "GI symptoms in COVID-19 have also been associated with elevated liver enzymes while increased markers of inflammation such as TNFα and IL-6 have separately been associated with severe and/or fatal disease." (PMID 36032119, 2022). "Future studies expanded these findings, demonstrating sustained increases in serum IL-2, IL-6, IL-10, and IFN-γ in severe COVID-19 cases, with higher IL-6 levels correlating with mortality risk." (PMID 35401519, 2022). "Eleven studies analyzed the association between the IL-6 level and COVID-19 mortality; these reported HR values from a Cox regression analysis." (PMID 35215138, 2022). "The aim of the study was to analyze the association between IL-6 and hematological and inflammatory parameters and outcomes of patients with COVID-19." (PMID 35873360, 2022). "A WHO-led meta-analysis of all trials of IL-6 antagonists confirms the benefits of Tocilizumab in severe forms of COVID-19, by reducing the risk of death by 15%." (PMID 36233539, 2022). "A significant associations between inflammatory cytokine IL-6 levels with amino acid metabolism was observed in COVID-19 patients." (PMID 36381071, 2022). "Our data showed a significant correlation between systemic BiP and IL-6, which confirms not only the association between BiP and COVID-19 severity but also suggests a connection between cellular stress and inflammation in the COVID-19 mechanism of disease." (PMID 36466830, 2022). "Other conditions found to be associated with COVID-19 are excessive IL-6 production, neutrophilia, and associated excessive neutrophil extracellular traps, which paralleled lung injury in patients with severe COVID-19." (PMID 35736648, 2022). "It is currently acknowledged that severe forms of COVID-19 are associated with the release of cytokines, such as IL-2, IL-6, IL-7, IL-10, tumor necrosis factor (TNF), and granulocyte colony-stimulating factor (GCSF)." (PMID 35743583, 2022). "The expression level of IL-6 shows an apparent upward trend in COVID-19 patients and is tightly associated with ARDS severity and poor prognosis." (PMID 36263178, 2022). "According to a systematic review, high serum levels of IL-6, presence of fever and current smoking are associated with at least 6, 9 and 12% of increased likelihood for development of severe COVID-19, respectively." (PMID 35021853, 2022). "On the other hand, IL-6 inhibitors are associated with an increased fungal infection risk, especially in COVID-19 patients." (PMID 36389687, 2022). "The studies indicate that the levels of IL-2, IL-6, IL-7, IL-10, and TNF-α are elevated in COVID-19; moreover, the increased IL-6 levels were found to be associated with disease progression and severe cases." (PMID 35656183, 2022).
COVID-19 (continued). "IL-6 significantly increases the risk of COVID-19 severity (aOR = 1.0284; 95% CI 1.0130–1.0441; p = 0.0003) and mortality (aOR = 1.0076; 95% CI 1.0004–1.0148; p = 0.04; adjusted hazard ratio (aHR) = 1.0036; 95% CI 1.0010–1.0061; p = 0.006)." (PMID 35215138, 2022). "Third, IL-6 has been identified as a COVID-19-associated cytokine by many independent studies, while other biomarkers have not been consistently reported in the literature." (PMID 35248063, 2022). "Inflammatory diseases including COVID-19 are associated with a cytokine storm characterized by high interleukin-6 (IL-6) titers." (PMID 35058480, 2022). "A decreased mortality rate in COVID-19 hospitalized patients was reported to be associated with the utilization of monoclonal antibody against IL-6 such as tocilizumab." (PMID 36295089, 2022). "Interleukin-6 (IL-6) is the key cytokine associated with COVID-19 disease severity, and high IL-6 levels have been detected in hyperglycemic patients with COVID-19." (PMID 36016249, 2022). "IL-6 has been found to have similar countless functions in the pathogenesis of the cytokine storm associated with both periodontitis and COVID-19, supporting the possible links between these two diseases." (PMID 35047633, 2022). "The use of glucocorticoids such as dexamethasone can reduce local and systemic IL-6 production and mitigate COVID-19-associated respiratory distress syndrome." (PMID 35336861, 2022). "Previous studies have established that elevated IL-6 levels are predictive criteria for COVID-19-associated cytokine storm." (PMID 35336861, 2022). "Recent retrospective studies proposed several risk factors associated with higher mortality and higher severity of COVID-19, including inflammatory markers such as interleukin-6 (IL-6), D-dimer, ferritin, and lactate dehydrogenase (LDH)." (PMID 35562677, 2022). "There are parameters, such as age, chronic cardiac and pulmonary diseases and elevated IL-6 and D-dimers, associated with the unfavourable evolution of COVID-19." (PMID 35807129, 2022). "Of note, IL-6, a major pro-inflammatory cytokine, has been demonstrated to be significantly associated with the development or severity of COVID-19 in many studies." (PMID 35989853, 2022). "Along with those 9 studies, an additional 28 studies analyzed the association between the IL-6 level and the severity and mortality of COVID-19." (PMID 35215138, 2022). "The meta-analysis result was that each increase in the IL-6 level of 1 pg/mL significantly increased the risk of mortality of COVID-19 patients (crude OR = 1.0152; 95% CI 1.0067–1.0237; p = 0.0004)." (PMID 35215138, 2022). "Our results suggest that advanced age, comorbidities and elevated serum IL-6 levels are associated with severe COVID-19 and are good markers to differentiate severe from mild cases." (PMID 35846757, 2022). "Our study suggests incorporating these CRP, IL-6 and D-dimer markers to design discriminatory tools and risk stratification tools to adequately identify COVID-19 patients with poor clinical outcomes." (PMID 35261542, 2022). "Overall, we identified a genetic variant in IL-6 that protects against critical conditions with COVID-19 though decreasing IL-6 expression in the serum." (PMID 35368020, 2022). "Two clusters were associated with a high risk of fatal COVID-19 (38–45% mortality) and were defined as the lowest humoral response with the lowest circulating T-cells (C1), or as high IL-6 inflammatory response (C2)." (PMID 36474964, 2022). "We also propose that the De Ritis ratio and the IL-6 level should be employed in guidelines for the risk stratification of COVID-19 patients to assist medical providers in decision making." (PMID 36366457, 2022). "Conversely, interleukin-6 inhibitors and blood transfusion in our COVID-19 patients have been all recognized as independent risk factors for developing VAP." (PMID 37386603, 2022).